IL15 (interleukin 15)
Diseases named in the same sentence as IL15 in open-access papers (continued):
Sharing a sentence is not in itself a finding about the gene and the disease.
cancer (continued). "A comprehensive list of all ongoing oncology clinical trials involving IL-15 is summarised for both solid and haematological cancers." (PMID 38745765, 2024). "The γc-cytokine interleukin-15 (IL-15) has various functions in the development and progression of hematological malignancies but also has a crucial role in the cytotoxic boost against cancer cells by serving as a growth factor for both T and NK cells." (PMID 39273395, 2024). "Many cytokines, including GM-CSF, IL-7, IL-12, IL-15, IL-18, and IL-21, have entered clinical trials for people with advanced cancer, while the FDA has approved interferon-alpha and IL-2." (PMID 38360737, 2024). "Our data showed that, unlike monomeric IL-15, the IL-15/IL-15Rα complex cannot antagonize the cancer cell-intrinsic IL-15-mediated promotion of cancer cell aggressiveness." (PMID 38637902, 2024). "The IPA summary of contralateral PTE+ cortical astrocytes shows predicted activation of serine peptidase inhibitor Kazal type 1 (SPINK1) general cancer pathway, as well as IL-15 production, KLF4, SOX4 and migration of phagocytes/myeloid cells." (PMID 38600221, 2024). "Cancer cell-intrinsic IL-15 and exogenous IL-15 differentially regulate cell motility and migration." (PMID 38637902, 2024). "We present a TALEN-based workflow to generate and maintain dual-edited (IL-15+/+/TGFβR2−/−) iPSCs that produce enhanced iPSC-derived natural killer (iNK) cells for cancer immunotherapy." (PMID 39260365, 2024). "Intracellular IL-15 in cancer cells was involved in regulating cell morphology and promoting cell motility and migration in vitro by activating ATK-mTORC1 signaling." (PMID 38637902, 2024). "IL-15, like IL-2, holds great potential for boosting NK cell function and enhancing the immune response against cancer." (PMID 38545115, 2024). "IL-15 has shown anti-cancer effects in many preclinical models, and presently, many clinical trials are testing its efficacy in cancer immunotherapy." (PMID 39273395, 2024). "Many cytokines, including GM-CSF, IL-7, IL-12, IL-15, IL-18, and IL-21, have entered clinical studies for people with advanced cancer." (PMID 38360737, 2024). "They incorporate critical elements, anti-cluster of differentiation 16 (CD16) and interleukin-15 (IL-15), which activate and enhance NK cell function, together with specific antibody to target each cancer." (PMID 38745768, 2024). "In conclusion, recombinant human IL-15 holds promise as a potential treatment for cancer and viral infections." (PMID 37251333, 2023). "This article delves into the mechanism of action, immune function, and research progress of IL-15 in cancer immunotherapy, along with a detailed overview of the current development status of IL-15 agonists." (PMID 37251333, 2023). "Univariate analyses revealed that factors with a significant role in HCC risk prediction in the two biological compartments are two cytokines, IL-5 and IL-15, previously found to play a controversial role in cancer pathogenesis." (PMID 37686245, 2023). "Given the safety challenges of recombinant IL-15, the pioneering development of N803 has enabled safe administration to patients and the clinical evaluation of the unrealized potential of IL-15 as a cancer therapeutic." (PMID 37371081, 2023). "IL-15 produced by cancer cells is a major driver for expansion and effector differentiation of intertumoral ILTCKs." (PMID 37892995, 2023). "It has been shown that priming of T cells with IL-21 and IL-15 before using in cancer T-cell therapy prolongs the life of these therapeutic T cells in a cancer mouse model." (PMID 37746258, 2023). "Accordingly, IL-15 has been proposed as a novel immunomodulatory cytokine in cancer immunotherapy and has been considered an adjuvant in vaccine regimens." (PMID 36767310, 2023).
cancer (continued). "The benefits of adoptive NK transfer include the improvement of anti-cancer responses of autologous NK cells through cytokine stimulation, e.g., IL-2, IL-12, IL-15, IL-18 and IFN-γ type I, which enhance the function and proliferation of natural killer cells." (PMID 36980527, 2023). "In cancer, chronic inflammation promotes expression of immune checkpoint molecules and their ligands, which limit the effectiveness of IL-15 therapy." (PMID 37616311, 2023). "Altogether, these data confirmed that the IL-15 NaMiX increase the capacity of PBMCs and NK cells to kill cancer cells and HIV-1 positive target cell lines." (PMID 37936122, 2023). "Interleukin-15 (IL-15) is a promising cytokine for the treatment of cancer as it stimulates NK and CD8+ lymphocytes." (PMID 37371081, 2023). "In this review, we will summarize the recent progress in interleukin-15 research over the past 5 years, highlighting its potential applications in cancer immunotherapy and the progress of interleukin-15 agonist development." (PMID 37251333, 2023). "In preclinical and clinical studies, IL-15 has been evaluated as a potential treatment against cancer as a monotherapy and in combination with other immunotherapeutic agents." (PMID 37409128, 2023). "Considering the ability of biNV-IL-15 to stimulate antitumor immunity, we constructed the cancer resection model to validate the anti-recurrence effects of biomimetic nanovaccine-mediated IL-15 self-transpresentation." (PMID 37875481, 2023). "Nevertheless, there are also significant differences between these two cytokines, making IL-15 more preferable for cancer immunotherapy." (PMID 37686586, 2023). "In IPA analysis, the top five enriched pathways included IL-15 production, circadian rhythm, Granzyme B Signaling, PD-1, PD-L1 cancer immunotherapy pathway and IGF-1 signaling." (PMID 38082307, 2023). "The promising clinical data and progress of IL-15 agonists will undoubtedly reinvigorate the field of cytokine engineering for use in cancer therapy." (PMID 37483629, 2023). "In fact, many preclinical studies and clinical studies have demonstrated that IL15 has a synergistic effect on immune therapy in cancers." (PMID 36959575, 2023). "In terms of cancer cachexia progression, research into the relationship between IL-15 and cancer cachexia is still in its early stages." (PMID 37755304, 2023). "Studies involving cancer patients undergoing anticancer therapies revealed that those patients who gained weight exhibited increased IL-15 values at 4 and 8 weeks during treatment, compared to both their baseline levels and patients who lost weight." (PMID 37755304, 2023). "Cytokines, such as interferon (IFN), interleukin 2 (IL‐2), and interleukin 15 (IL‐15), have been extensively studied in clinical settings of other cancers." (PMID 38037752, 2023). "Discovering small molecules that enhance transcription factor activity (e.g., Bhlhe40) and increase soluble factors (TGF-β, IL-2, IL-15) presents a unique avenue for novel anti-cancer therapies." (PMID 37892995, 2023). "TGFβ downregulates the expression of NKG2D on NK cells and CD8+ T cells in several cancer models, and has been shown to suppress IL-15 and STAT5-mediated NK cell activation through the blockade of mTOR activation." (PMID 36980629, 2023). "Cancer immune therapy utilizing interleukin 15 (Il-15) is hampered by the short half-life and systemic toxic effects of the cytokine." (PMID 37875481, 2023). "A number of preclinical cancer experiments performed extensive investigations on the potential of IL-15 as an antitumor agent that is mediated by NK cells and T lymphocytes, which recently entered trial studies for the mediation of cancer regression." (PMID 36742134, 2023). "It was recently shown that IL-15 was mainly expressed by cancer cells, as well as macrophages in tumors, which is consistent with our findings." (PMID 37348499, 2023).
cancer (continued). "Serum IL-15 (cancer-suppressive), IL-17, B-cell activating factor were found to be elevated in DM relative to healthy patients." (PMID 37681925, 2023). "Herein, we review the current knowledge on the use of IL-15 as a cancer therapy, with a particular focus on the mechanism(s) of action and preclinical and clinical development of N803 (Anktiva®, formerly known as ALT803), an IL-15 heterodimeric agonist." (PMID 37371081, 2023). "It is a fusion protein containing IL-12, IL-15, and IL-18 receptors, which can activate and amplifies memory-like (ML) NK cells, prolong life and enhances anti-cancer function in vitro." (PMID 37251333, 2023). "Previous studies have demonstrated the impact of using IL-15 in combination immunotherapies for cancer." (PMID 37465665, 2023). "The findings from our study highlight the effectiveness of a combination of donor selection based on CD16 expression, CAR engineering, and IL-15 secretion in enhancing the cancer therapy potential of Vδ2 T cells." (PMID 37938576, 2023). "Clinical trials have been conducted or are currently underway using IL-15 as monotherapy or in combination with ipilimumab and nivolumab in patients with advanced solid tumors rendering IL-15 a promising anti-cancer immunotherapy." (PMID 37465665, 2023). "Cytokines themselves traditionally have played a key role in cancer immunotherapy, with some being used as monotherapies (e.g., IL-2, IL-15) or in combinations with monoclonal antibodies (e.g., rituximab) or chemotherapeutics." (PMID 37237491, 2023). "Consistent with previous findings, we demonstrated that T cell modulators, IL15 and CXCL10, are often deleted in cancers, and these deletion events coincide with TLS loss in tumors." (PMID 37348499, 2023). "The pleiotropic and unique biology of IL-15 render this cytokine very attractive for the agnostic treatment of cancer." (PMID 37371081, 2023). "It has been shown that combination therapies of IL-15 or IL-2 administration with PD-1/PD-L1 blockade was efficacious in murine cancer and infection models." (PMID 36454338, 2023). "These regulatory mechanisms are an important limiting factor in cytokine monotherapy aiming to promote CD8+ T cell control of cancer, including IL-15 therapy." (PMID 37616311, 2023). "Cytokine therapy, involving interleukin-15 (IL-15), is a promising strategy for cancer immunotherapy." (PMID 37875481, 2023). "Clinical trials and animal models have achieved positive results by injecting IL-15 to treat cancer." (PMID 37585912, 2023). "In conclusion, IL-15-based agents are potent cancer immunotherapies, especially with the emergence of next-generation IL-15 cytokines." (PMID 36936961, 2023). "IL-15, a stimulatory cytokine, has garnered considerable interest in recent years as a potential cancer immunotherapy drug, and was rated as the most promising candidate by the National Cancer Institute in 2008." (PMID 37251333, 2023). "Multiple IL-15-armored CAR-NK products have been tested in clinical trials with reported safety profiles in cancer patients." (PMID 37564658, 2023). "Recent studies have revealed that interleukin-15 also plays a critical role in cancer immunotherapy." (PMID 37251333, 2023). "The significant cancer therapy potential of the combination of IL-12 and IL-15 promises to take advantage of IL-12’s ability to prime innate/adaptive immune responses, while IL-15 can boost and maintain an antitumor response." (PMID 38250068, 2023). "IL-15 has also been investigated as a potential therapeutic agent for the treatment of various types of cancer." (PMID 37251333, 2023). "N-803 has shown broad anti-tumor effects in several murine cancer models, as well as increased tissue retention compared to soluble IL-15." (PMID 37766318, 2023). "We found that IL-15-treated NK-92 cells doubled the rate of K-562 cancer cells killing under both paradigms." (PMID 35197969, 2022).
cancer (continued). "ALT-803 is a novel interleukin-15 (IL-15) superagonist complex to regulate lymphocytes and kill cancer cells." (PMID 35804953, 2022). "The data agree with the results obtained in clinical studies using other IL-15 variants and also suggest that combinations should be explored for enhancing IL-15 anti-cancer effects in humans." (PMID 36713398, 2022). "Gene Set Enrichment Analysis (GSEA) was performed to evaluate the biological functions of IL-15 in pan-cancer." (PMID 36467072, 2022). "According to these results, an interesting strategy for cancer treatment would be the development of NK-cells expressing membrane-bound IL-15/IL-15Rα superagonists." (PMID 35919494, 2022). "IL-15, which is a 15-kDa cytokine, is a four-helix bundle common gamma chain cytokine and a promising target for cancer immunotherapy." (PMID 36439125, 2022). "NK cells consist of numerous subpopulations and are well-known targets of IL-15 therapy, which is used to treat cancer." (PMID 36429085, 2022). "The cytokines IL-1β and IL-15 are important in the development of inflammatory and protective immune responses to microbes and cancer." (PMID 36119067, 2022). "Some cytokines including GM-CSF, IFN-α, IL-2, IL-7, IL-12, IL-15, IL-18, and IL-21 have antitumor activity via stimulating immunity, inhibiting proliferation, or inducing apoptosis in cancer cells." (PMID 35062949, 2022). "In this article, we try to systematically analyze if IL-15 is a potential molecular biomarker for predicting patient prognosis in pan-cancer and its connection with anti-cancer effects of exercise." (PMID 36467072, 2022). "This study highlights the positive roles of IL-15 in pan-cancer and provides data-based insights for the application of IL-15 in cancer treatment." (PMID 36467072, 2022). "Similar to hu-BLT, supplementation of IL-15 can also increases the cytotoxic function of NK cells and their numbers in human cancer patients." (PMID 36612108, 2022). "Meanwhile, several preclinical studies have addressed the use of heterodimeric IL-15 in cancer immunotherapy." (PMID 36115839, 2022). "Other clinical trials using IL-15 in treatment of cancer have shown increased activation of NK and CD8+ T cells, but when administered as monotherapy have been ineffective." (PMID 35747794, 2022). "These so-called IL-15 DCs have already proven to exhibit several favorable properties as cancer vaccine." (PMID 35250967, 2022). "Interleukin IL-15 (IL-15), a cytokine that supports cytotoxic immune cells, has been successfully tested as an anti-cancer and anti-metastatic agent, but combinations with conventional chemotherapy and surgery protocols have not been extensively studied." (PMID 36713398, 2022). "These experiments showed that both IL-15 and cell-to-cell contact signals delivered by cancer cells were important for the development of immature CD56bright NK cells into highly cytotoxic ieILC1s." (PMID 36372017, 2022). "Recently, some completed clinical trials have reported usage of recombinant human single-chain IL-15 and IL-15 superagonist in cancer treatment." (PMID 36467072, 2022). "Next, we sought to analyze the relationship between mRNA expression levels of IL-15 and the prognosis of patients with cancer." (PMID 36467072, 2022). "The correlation between the mRNA expression level of IL-15 and patients’ clinicopathological features progression was further investigated in pan-cancer." (PMID 36467072, 2022). "SOT101 is a superagonist fusion protein of interleukin (IL)-15 and the IL-15 receptor α (IL-15Rα) sushi+ domain, representing a promising clinical candidate for the treatment of cancer." (PMID 36300122, 2022). "Because of these benefits, IL-15 was ranked first for having the greatest potential in cancer immunotherapy by the US National Cancer Institute in 2008." (PMID 35806311, 2022).
cancer (continued). "Second, in the context of the high interest in the clinical study results of the combined treatment with IL-7 or IL-15 and ICIs in advanced cancers, α can directly suggest a subgroup that can expect a good treatment response to immunotherapy." (PMID 36291893, 2022). "This IL-15/IL-15Rα complex resulted in increased survival of memory T cells and NK cell, leading to improved outcomes in mouse models of cancer." (PMID 36172388, 2022). "The main (Top-5) biological processes affected by IL-15 were explored by GSEA analysis in pan-cancer." (PMID 36467072, 2022). "Interleukin-15 (IL-15), the pleiotropic cytokine with various biological functions, shows promising impacts on cancer immunotherapy." (PMID 35806311, 2022). "Interleukin 15 (IL-15) is a multifunctional cytokine that is a strong candidate for cancer immunotherapy." (PMID 35413499, 2022). "Anti-ARH77 T cells and CIK cells stimulated with IL-15 mDCs (6 days) displayed higher IFN-γ spot production against ARH77 cancer cells compared with the other groups." (PMID 35413499, 2022). "Currently, rare studies have checked the IL-15 expression in pan-cancer using tissue microassays except in those databases." (PMID 36467072, 2022). "This complex has been proven to have improved stability, longer persistence in lymphoid tissues, and enhanced anti-cancer activity comparing to native IL-15 in vivo." (PMID 35804808, 2022). "In this review, we discuss the biology of IL-15 and its receptors, IL-15 and its derivative products for cancer immunotherapy, as well as the adoptive transfer of IL-15-armored immune cells in cell therapies." (PMID 35806311, 2022). "Given its positive effects on anticancer immunity, IL15 was ranked as the most promising immunotherapy for cancer treatment by an immunologist panel at a National Cancer Institute workshop." (PMID 35174623, 2022). "Cytokine receptor interaction and Gαs signaling were the most common signaling pathways of IL-15 for pan-cancer, followed by olfactory transduction, neutrophil degranulation, immunoregulatory interactions pathway." (PMID 36467072, 2022). "Recently, clinical trials have been undertaken to improve treatment outcomes using IL-7 or IL-15 and ICIs in combination in various cancers (NCT03901573, NCT04594811, NCT04332653, NCT04984811)." (PMID 36291893, 2022). "Then, via analyzing the RNA-seq data of TCGA and GTex databases, the expression of IL-15 in pan-cancer was assessed deeper." (PMID 36467072, 2022). "Notable increases in the fold change of circulating levels of IL-2, IL-15, and IL-18 were also documented following SBRT and immunotherapy; these cytokines have been associated with promising cancer immunotherapeutic approaches." (PMID 35055015, 2022). "Many studies have investigated the co-expression of one or more cytokines (such as IL-2, IL-7, IL-12, IL-15, IL-18, IL-21, and IL-23), or the combination of their receptors to generate gene-edited interleukin-armored immune cells against cancer." (PMID 35806311, 2022). "Both IL-15 and IL-21 are members of the IL-2 family and have been investigated to evaluate their therapeutic potentials for cancer treatment." (PMID 35795050, 2022). "Combined with its correlation with exercise, we provide a theoretical basis for exercise to prevent cancer and IL-15 as a pan-cancer therapeutic target." (PMID 36467072, 2022). "We also present the limitations and future directions of incorporating IL-15 in cell-based cancer immunotherapy." (PMID 35806311, 2022). "IL-15 has a short serum half-life and cancer patients that received intravenous infusion of recombinant IL-15 experienced dose-limiting toxicity." (PMID 33858437, 2021). "B16F10-OVA and CT26-OVA cancer cells were infected with IL-15 BV + IL-15Rα BV (termed IL-15:IL-15Rα-B16F10-OVA and IL-15:IL-15Rα-CT26-OVA, respectively)." (PMID 34439192, 2021).